NQO1 (NAD(P)H quinone dehydrogenase 1)
Diseases named in the same sentence as NQO1 in open-access papers (continued):
Sharing a sentence is not in itself a finding about the gene and the disease.
melanoma (continued). "On the other hand, the downregulation of NQO1/NFR2 and their concurrence with ARNT were also associated with malignant melanoma." (PMID 33446631, 2021). "In clinical tissue specimens, increased ARNT, pyruvate dehydrogenase kinase 1 (PDK1), and NAD(P)H quinine oxidoreductase-1 (NQO1) was observed in benign nevi, whereas lower expression was observed in melanoma." (PMID 33446631, 2021). "Since CA induces NQO1 expression in melanoma cells in vitro, it affects the cell proliferation and sensitizes melanoma cells to other antitumor drugs." (PMID 31408993, 2019). "RD itself was found to activate the expression of NRF2 and NQO1 in B16 melanoma cells, although the effects of RD were weaker than carnoic acid." (PMID 29439519, 2018). "Melanoma cell line A7 and NSCLC cell lines A549 and H460 harbor KEAP1 loss-of-function mutation and express abundant NRF2 and NQO1 in comparison with other cell lines." (PMID 27045471, 2016). "NQO1 is highly expressed in normal melanocytes and in several melanoma cell lines despite the presence of wild-type KEAP1, and the NQO1 expression is dependent on NRF2 activation." (PMID 27045471, 2016). "NQO1-low melanoma cell lines were treated with a combination of 17-AAG and CDDP or 17-AAG and DTIC at molar ratio of 1:100 or 1:1,000, respectively, and the combination index was calculated according to the Chou-Talalay method." (PMID 27045471, 2016). "In both melanoma and NSCLC, IC50 values for cell lines with KEAP1 mutation and high NQO1 expression were lower than those of cell lines with low NQO1 expression." (PMID 27045471, 2016). "In contrast, elevated expression of NQO1 has been reported in several kinds of cancer including melanoma, 30% of primary melanomas showing strong immunopositivity for NQO1." (PMID 27045471, 2016). "We expected that treatment with CDDP or DTIC, either alone or in combination with 17-AAG, would synergistically eliminate NQO1-low melanoma cell lines through induction of NQO1 expression." (PMID 27045471, 2016). "Overexpression of NQO1 in KEAP1 wild-type melanoma cell lines and normal melanocyte was dependent on NRF2." (PMID 27045471, 2016). "In conclusion, NQO1 overexpression in melanoma appears to be NRF2-dependent and inversely correlated with 17-AAG sensitivity." (PMID 27045471, 2016). "Our previous studies found that 12 markers including pAkt, Bim, BRG1, BRMS1, CTHRC1, Cul1, ING4, MCL1, NQO1, SKP2, SNF5 and SOX4 were associated with melanoma progression." (PMID 23028750, 2012). "Additionally, the impact of Slc7a11 and Nqo1 knockdown on the cytotoxicity of leukoderma-inducing phenols was examined in B16-4A5 melanoma cells." (PMID 39858507, 2025). "The conditional overexpression of NQO1 in melanoma cells reduces RD toxicity." (PMID 39858507, 2025). "NQO1, a cytoplasmic flavoprotein, is overexpressed in various cancers, including breast, pancreatic, hepatocellular, bladder, ovarian, thyroid, colorectal, cholangiocarcinoma, cervical, melanoma, and lung." (PMID 40007539, 2025). "Both NQO1 and SOCS3 are associated with lower malignancy grade in melanoma." (PMID 37894348, 2023). "Along with these two enzymes, also NQO1 could play a significant role in CoQ10 reduction on the plasma membrane of melanoma cells, since it was published that NQO1 is important for melanoma survival." (PMID 35255427, 2022). "To demonstrate the existence of a UBIAD1/CoQ10/NQO1 axis that regulates and maintains cell survival in ROS-dependent melanoma cell lines, we sought to understand whether the two enzymes could have a synergistic effect." (PMID 35255427, 2022). "According to our hypothesis, we found that NQO1KD induced ROS increase and lipid peroxidation and that NQO1 is required for survival in melanoma cells." (PMID 35255427, 2022). "We envision UBIAD1 and NQO1 blockade as novel therapeutic strategies in melanoma." (PMID 35255427, 2022).
melanoma (continued). "Interestingly, melanoma cells harboring P187S variant of NQO1 were susceptible to 17-AG-induced apoptosis, although the occurrence of cell death was delayed compared with melanoma cells harboring wild-type NQO1." (PMID 31659567, 2020). "Accordingly, sensitivity of melanoma cells to 17-AAG was related to NQO1 overexpression." (PMID 31659567, 2020). "They found that treatment of B16BL6 mouse melanoma cells or normal human melanocytes with carnoic acid, a transcriptional inducer of the NQO1 gene through activation of the transcription factor, nuclear factor E2-related factor 2 (NRF2), significantly mitigated the cytotoxicity of RD." (PMID 29439519, 2018). "Because NRF2 activation is associated with resistance to ROS-based chemotherapy and radiotherapy, 17-AAG could be a potential second-line treatment for NQO1-high melanoma, or in combination with CDDP for NQO1-low melanoma." (PMID 27045471, 2016). "Because either CDDP or DTIC produces reactive oxygen species that activate NRF2, we determined whether these agents would sensitize NQO1-low melanoma cells to 17-AAG." (PMID 27045471, 2016). "Expression of NRF2 and NQO1 proteins in normal melanocytes, melanoma and NSCLC cell lines with or without KEAP1 mutations was compared by immunoblotting." (PMID 27045471, 2016). "The present study was conducted to clarify whether an HSP90 inhibitor, 17-AAG, efficiently eliminates melanoma with KEAP1 mutation, as the NRF2 target gene, NQO1, is a key enzyme in 17-AAG bioactivation." (PMID 27045471, 2016). "Because either CDDP or DTIC produces ROS, which activate NRF2 and induce NQO1 expression, we determined whether these drugs might sensitize NQO1-low melanoma cells to 17-AAG." (PMID 27045471, 2016). "As observed in the present study, KEAP1 mutation-independent NRF2 activation may be evident in a high proportion of NQO1-high melanomas." (PMID 27045471, 2016). "For example, streptonigrin was more cytotoxic against melanoma cells than against leukemia K562 cells which might indicate a cancer type specificity, probably connected with the NQO1 level." (PMID 24595456, 2014). "However, it still remains to be further explored the functional cross-talk between UBIAD1 and NQO1 in melanoma progression and whether the blocking of these enzymes would represent a valid therapeutic approach to treat melanoma." (PMID 35255427, 2022). "Expression of NRF2 and NQO1 was variable among melanoma cell lines without KEAP1 or NRF2 mutation." (PMID 27045471, 2016). "Recent studies have revealed that NQO1 is expressed at a high level in most human solid tumors including those of the colon, breast, pancreas, ovaries and thyroid, and it has also been detected following the induction of cell cycle progression and proliferation of melanoma cells." (PMID 24912939, 2014). "As NQO1 is over-expressed in most melanoma cell lines in comparison with normal melanocytes, even low concentration of streptonigrin might be sufficient to kill melanoma cells." (PMID 24595456, 2014). "Interestingly, NQO1 was found to be expressed at high levels in many solid tumors, including cholangiocarcinoma, lung and pancreas, and has also been detected following the induction of cell cycle progression and proliferation of melanoma cells." (PMID 24912939, 2014). "Testing the obtained hybrids against several cancer cell lines with different levels of the NQO1 protein (A549-lung, MCF7-breast, C32-melanoma), the authors reported the highest activity against lung cancer for most hybrids." (PMID 36235089, 2022). "Last, we evaluated the changes in mRNA expression of UBIAD1, NQO1 and FSP1 upon UBIAD1KD or NQO1KD in melanoma cells." (PMID 35255427, 2022).
melanoma (continued). "As marliolide was reported to increase antioxidant activity by promoting the expression of antioxidant enzymes, such as HO-1 and Nqo1, we first investigated its hypopigmentation effects on B16F0 melanoma cells." (PMID 33924406, 2021). "Studies showed that NQO1 activates 17-AAG and also sensitizes the response of malignant melanoma cells to 17-AAG." (PMID 30704449, 2019). "The present study has clarified that melanoma and NSCLC cell lines showing NQO1 overexpression are sensitive to 17-AAG in comparison with cell lines showing low NQO1 expression." (PMID 27045471, 2016). "Immunohistochemical expressions of 12 promising biomarkers (pAkt, Bim, BRG1, BRMS1, CTHRC1, Cul1, ING4, MCL1, NQO1, SKP2, SNF5 and SOX4) were studied in 122 melanomas and 33 dysplastic nevi on tissue microarrays." (PMID 23028750, 2012). "Factors secreted by these cells downregulated NQO1 and SOCS3 expression in some of the melanomas." (PMID 37894348, 2023). "Factors secreted by these cells upregulated NQO1 and SOCS3 expression in melanoma." (PMID 37894348, 2023). "However, the concomitant mild silencing of both UBIAD1 and NQO1 enzymes had a dramatic effect on cell survival (UBIAD1KD Low + NQO1KD Low), suggesting a synergistic effect of the two enzymes in protecting melanoma cells from cell death." (PMID 35255427, 2022). "Additionally, we show that the NAD(P)H Quinone Dehydrogenase 1 (NQO1), responsible for the 2-electron reduction of CoQ10 on plasma membranes, acts downstream of UBIAD1 to support melanoma survival." (PMID 35255427, 2022). "In particular, it could be interesting to study UBIAD1/CoQ10/NQO1 axis in those situations where oxidative stress drives resistance to therapy (e.g. BRAF and MEK inhibitors-resistant melanoma)." (PMID 35255427, 2022). "Melanoma cell response to CCT018159 was independent of NQO1 expression and the level of P-glycoprotein/ABCB1 (ATP binding cassette subfamily B member 1) involved in drug efflux." (PMID 31659567, 2020). "In NQO1low melanoma cells, combination of 17-AAG and cisplatin exerted cooperation, which was driven by cisplatin-mediated induction of reactive oxygen species and up-regulation of NQO1." (PMID 31659567, 2020). "In melanoma and non-small cell lung carcinoma cell lines with or without KEAP1 mutations, NQO1 expression and 17-AAG sensitivity are inversely correlated." (PMID 27045471, 2016). "We then determined whether NQO1 overexpression is dependent on NRF2 transcriptional activity in melanocytes and melanoma harboring wild-type KEAP1." (PMID 27045471, 2016). "NQO1 expression and 17-AAG sensitivity in melanoma and NSCLC cell lines." (PMID 27045471, 2016). "We hypothesized that in melanoma cells also NQO1, transcriptional target of NRF2, could be responsible for the regeneration of the reduced form of CoQ10, since NQO1 is part of a plasma membrane redox system and elevated levels of NQO1 are associated with poor melanoma patient outcome." (PMID 35255427, 2022). "NQO1 was found to be highly expressed in normal melanocytes and several melanoma cell lines, irrespective of the presence of wild-type KEAP1, and they were also 17-AAG-sensitive in comparison with NQO1-low cell lines." (PMID 27045471, 2016). "However, treatment of melanoma cells with the cell-permeable antioxidant N-acetylcysteine, or the PI3K inhibitor LY294002, failed to prevent NQO1 transcription." (PMID 27045471, 2016).
colorectal cancer (28 papers, 2008 to 2025). A primary or metastatic malignant neoplasm that affects the colon or rectum. "A similar distribution occurred in both groups, therefore a significant effect was found between the 609C > T polymorphism of the NQO1 gene and the risk for developing colorectal cancer." (PMID 34356648, 2021). "The analysis of the clinical parameters concerning the location and characteristics of the tumor stage revealed a statistically significant increase in the risk for colorectal cancer in the carriers of the TT genotype of the NQO1 polymorphism." (PMID 34356648, 2021). "The effect of the C and T alleles and the 609C > T polymorphism of the NQO1 gene on the risk of colorectal cancer was analyzed." (PMID 34356648, 2021). "To date, various studies have been conducted to assess the relationship between the NQO1 609C > T polymorphism and the risk for colorectal cancer, but the results are inconsistent." (PMID 34356648, 2021). "The aim of the study was to evaluate the correlation between the 609C > T polymorphism of the NQO1 gene and colorectal cancer risk in the Polish population." (PMID 34356648, 2021). "These authors suggest that the 609C > T NQO1 polymorphism plays an important role in the development of colorectal cancer in the Chinese population." (PMID 34356648, 2021). "In case of the carriers of the TT genotype of the NQO1 polymorphism, an elevated risk for colorectal cancer was observed (OR = 2.96; 95% CI: 1.02–10.40)." (PMID 34356648, 2021). "In the present study, we analyzed the clinical valuesand frequency of NQO1 609C > T polymorphism in patients diagnosed with colorectal cancer and controls." (PMID 34356648, 2021). "An analysis of the impact of individual genotypes: CC, CT, and TT of the 609C > T polymorphism of the NQO1 gene on the risk for developing colorectal cancer was also performed." (PMID 34356648, 2021). "The literature offers reports on the relationship between the NQO1 609C > T polymorphism and colorectal cancer." (PMID 34356648, 2021). "NQO1 inactivation has been associated with increased susceptibility to a variety of carcinogens, and has been related to the risk of colorectal cancer." (PMID 21931799, 2011). "A meta-analysis suggested an increased susceptibility to colorectal cancer as well as lung and bladder cancers associated with NQO1 187Ser allele, although the results from individual studies were heterogeneous." (PMID 20534171, 2010). "The prevalence of the 609T allele of NQO1 has been studied in tumors of lung, bladder, and colorectal cancer as well as leukaemia." (PMID 18416817, 2008). "The results of the analysis indicate that the NQO1 609C > T polymorphism was significantly associated with the risk of colorectal cancer (total OR = 1.30, 95% CI = 1.07–1.59) for CT vs. CC, 1.64 (1.15–2.33) for TT vs. CC, 1.34 (1.10–1.64) for TT/CT vs. CC, and 1.43 (1.10–1.87) for TT vs. CT/CC)." (PMID 34356648, 2021). "Our results also confirm that the TT genotype of the 609C > T polymorphism of the NQO1 gene may be associated with an increased risk of colorectal cancer and its metastasis." (PMID 34356648, 2021). "Therefore, the aim of the study was to evaluate the correlation between the 609C > T polymorphism of the NQO1 gene and colorectal cancer risk." (PMID 34356648, 2021). "In addition, the 609C > T NQO1 polymorphism in chronic smokers and alcohol drinkers has been shown to have a greater impact on the risk for developing colorectal cancer than the polymorphism alone." (PMID 34356648, 2021). "In agreement with previous studies, lower activities of GPx and CAT as well as higher activities of SOD were observed in patients with oesophageal, gastric, and colorectal cancers compared with control subjects and low NQO1 activity was linked to increased risk of acute leukemia." (PMID 27057281, 2016).
colorectal cancer (continued). "NQO1 polymorphism, which can cause reduction of its activity, was reported to affect susceptibility to lung, bladder, and colorectal cancers that could either increase or decrease cancer risks associated with ethnicity and exposure to carcinogens." (PMID 27057281, 2016). "NQO1*2, the C609T substituted polymorphic form of NQO1, has low NQO1 enzymatic activity compared with wild-type and has been associated with greater risk of cancer incidence including pediatric leukemia, colorectal cancer, and gastric cardiac carcinoma." (PMID 20966874, 2010). "Hence, the TT genotype of the 609C > T polymorphism of the NQO1 gene may be associated with an increased risk of colorectal cancer and its metastasis." (PMID 34356648, 2021). "Though previous studies demonstrate the importance of NQO1 signaling for the progressive phenotype in colorectal cancer and GSTP1 is overexpressed in many cancers and linked to drug resistance, the molecular mechanisms of how these reductive enzymes involved in GBM proliferation remain unclear." (PMID 33087132, 2020). "Therefore, the functional NQO1 609 C>T polymorphism resulting in decreased activity of NQO1 enzyme may increase risk of colorectum cancer." (PMID 22272361, 2012). "In this follow-up research, we observed the interaction of these gene polymorphisms (COMT, GSTM1, GSTT1, MGMT, NQO1, and XRCC1) with different meat diets and on outcomes linked to colorectal cancer risk: ATNC levels, DNA adduct levels, and DNA strand breaks." (PMID 38337709, 2024). "NQO1 mRNA was highly expressed in the fibroblast cells of skin cutaneous melanoma, and NQO1 was highly expressed in endothelial cells in colorectal cancer." (PMID 37583897, 2023). "The NQO1 mRNA was highly expressed in malignant cells in head and neck squamous cell carcinoma, colorectal cancer, skin cutaneous melanoma, stomach adenocarcinoma, and cholangiocarcinoma." (PMID 37583897, 2023). "In accord with these findings, the present study showed that knockdown of NQO1 reduced the proliferative ability of RKO colorectal cancer cells." (PMID 36793872, 2023). "The single-cell analysis revealed a potential relationship between the NQO1 mRNA expression levels and the infiltration of immune cells and stromal cells in bladder urothelial carcinoma, invasive breast carcinoma, and colorectal cancer." (PMID 37583897, 2023). "We noticed that among the 16 single-cell datasets with high expression of NQO1, there were two datasets for invasive breast carcinoma, colorectal carcinoma, and glioma, respectively." (PMID 37583897, 2023). "The overexpression of pirin in human colorectal cancer correlated with the overexpression of Nrf2 and the classical Nrf2 target gene, NQO1, suggesting that increased transcription of both PIR and NQO1 is a consequence of Nrf2 activation." (PMID 35204145, 2022). "Colorectal cancer patients with elevated NQO1 expression have been shown to correlate with high-level of HIF-1α expression and poor prognosis." (PMID 31909204, 2020). "Conversely, RKO colorectal cancer cells with suppressed NQO1 expression showed markedly accelerated degradation of HIF-1α." (PMID 27966538, 2016). "Immunohistochemical analysis of colorectal cancer tissues demonstrates that high NQO1-expressing tumours, indicating 3 and 4 of IHC scores, contain a significantly elevated expression of HIF-1α." (PMID 27966538, 2016). "First, we generated RKO human colorectal cancer cells that express short hairpin RNA (shRNA) targeting NQO1 (RKO/pshNQO1) and the control scramble shRNA (RKO/pshCont)." (PMID 27966538, 2016). "In order to better understand the potential clinical implication of NQO1 for the prognosis of human cancer, we revisited publically available data sets for colorectal cancer." (PMID 27966538, 2016). "First, we found that the expression levels of NQO1 are significantly higher in colorectal cancer specimens compared with the matched normal colorectal specimens." (PMID 27966538, 2016).